ELN (elastin)
Diseases named in the same sentence as ELN in open-access papers (continued):
Sharing a sentence is not in itself a finding about the gene and the disease.
tumor (197 papers, 2004 to 2026). "VPI represents the ability of the tumor to penetrate the pleural elastin layer, indicating an elevated risk of seeding into the pleural cavity." (PMID 38166960, 2024). "Elastin fibers are implicated in tumor invasion and metastasis, cell proliferation, adhesion, apoptosis, and angiogenesis." (PMID 34827210, 2021). "Uncontrolled tumor cell proliferation and limited tissue blood supply induces intra-tumoral hypoxia, which in turn induces expression of the gene encoding the collagen and elastin cross-linking enzyme lysyl oxidase (LOX) in human tumor cells." (PMID 30356678, 2018). "A significant loss of the original collagen fibers and elastin fibers occurred; however, the invasion by tumor resulted in desmoplasia, and thus the glands are surrounded by collagen fibers." (PMID 29291032, 2017). "LOX is a secreted amine oxidase that plays a key role in modifying the primary tumor microenvironment by crosslinking collagens and elastin in the ECM thereby causing stiffening of the matrix and enhancing the invasive and metastatic properties of the tumor." (PMID 25790191, 2015). "Compared to cell-based therapies, which have issues with viability, retention, risk of tumor formation, and precise delivery within the wound environment, collagen-elastin scaffolds serve as supportive, biocompatible matrices that support proliferation and differentiation of host cells." (PMID 40917518, 2025). "Indeed, high elastin expression in the tumor matrix was significantly associated with smaller tumors, measuring less than 3 cm." (PMID 40895158, 2025). "However, mutations in genes CPNE1, CTSB and ELN, indicated that their expression was slightly higher in tumor samples than in normal ones." (PMID 38544823, 2024). "Our findings revealed a substantial enhancement in venous invasion detection rates, with Van Gieson’s elastin staining associated with a notable 4.5-fold increase in venous invasion identification upon implementing routine staining on all tumor-containing blocks compared to H&E alone." (PMID 37894944, 2023). "ELN encodes the elastin protein, which is a key protein in the tumor microenvironment." (PMID 34164341, 2021). "Cath -S also promotes tumor cell invasion, metastasis and angiogenesis; once secreted into the extracellular milieu it causes degradation of extracellular matrix proteins including laminin, fibronectin, elastin, and some collagens." (PMID 27490795, 2016). "The constituents of the ECM including elastin, collagen, laminin, fibronectin, and proteoglycans, are the macromolecules secreted by tumor cells and tumor-associated fibroblasts, which can not only support and protect tumor cells but also promote tumor invasion and metastasis." (PMID 36908706, 2023). "Elastin and collagen are the main components of elastic fibers and their DNA methylation changes indicate altered extracellular matrix barrier function which may be associated with tumor progression." (PMID 30911103, 2019). "We consider that the main fluorophores contributing to organoid fluorescence may be NADH and flavins from the new tumour urothelium, while control fluorescence may contain a higher contribution from the underlying collagen and elastin matrix of the lamina propria and extra-cellular matrix (ECM)." (PMID 27446646, 2016). "Studies addressing intrinsic and extrinsic skin aging consistently reported collagen fragmentation, elastin disorganization, and reduced fibroblast responsiveness, leading to impaired mechanotransduction and diminished capacity for ECM reorganization." (PMID 41572953, 2026). "Conversely, the mean of elastin density and mean of collagen density displayed a declining trend, indicating alterations in the extracellular matrix composition during tumor progression." (PMID 39744437, 2025). "The ECM is composed of several molecules, including collagens, elastin and fibronectin, whose deposition or degradation can be modulated to facilitate tumor progression." (PMID 40083939, 2025).
tumor (continued). "Phasor-FLIM analysis indicates that normal tissue maintains a balance between elastin and collagen, whereas in tumor conditions, aberrant elastin secretion is often observed." (PMID 40895158, 2025). "The amount of ECM present in the tumor, particularly collagen, elastin, and hyaluronic acid, is the primary factor that determines how stiff the tumor is." (PMID 39801760, 2025). "These synergistic effects of collagen and elastin within the ‘matrix amalgam’ orchestrate the mechanical and biochemical environment that supports tumor progression." (PMID 40542654, 2025). "Among the upregulated proteins in the LLN group, LOX (lysyl oxidase enzymes), which catalyze the crosslinking of collagens and elastin, increasing the tissue stiffness, has been proven to promote tumor progression through increased integrin signaling and EMT." (PMID 40075679, 2025). "The increased expression of MMPs 2 and 9 acts by breaking down structural components of the extracellular matrix, such as collagen, fibronectin, elastin, and proteoglycans, creating a more permissive environment for cellular tumor migration and invasion." (PMID 40940722, 2025). "Specifically, in four patient samples, we confirmed a pronounced accumulation of elastin within the tumor region, supporting the findings obtained through label-free analysis." (PMID 40895158, 2025). "By integrating FLIM with second harmonic generation (SHG) imaging, we characterized the fiber compositions in healthy versus tumor tissues, distinguishing between collagen and elastin autofluorescence signatures." (PMID 40895158, 2025). "MMP-7 is an enzyme responsible for the degradation of extracellular matrix components, including collagen, laminin, and elastin, which facilitates tumor invasion and metastasis." (PMID 41007705, 2025). "When MMPs are activated, these insertions can conjugate with and lyse gelatin, collagen and elastin, degrade the extracellular matrix, regulate adhesion between tumor cells and promote angiogenesis and cell invasion." (PMID 38568917, 2024). "Tumor extracellular matrix is composed of collagen, elastin, proteoglycans, and glycoproteins and is used for the complex, interconnected macromolecular network surrounding and supporting cells in organs and tissues." (PMID 38440405, 2024). "The combination of these two agents decreased the expression levels of collagen, fibronectin, and elastin in both tumor spheroid and xenograft tumor models." (PMID 39062169, 2024). "This theranostic agent leverages the γ-ray and β-particles emitted by iodine-131, combining SPECT imaging for elastin-specific visualization with 131I-mediated brachytherapy that significantly inhibits tumor growth in VX2 tumor-bearing rabbits." (PMID 39770505, 2024). "We detected that TNFRSF12A, IL1R1, ELN and CYP26B1 were unfavorable prognostic factors that were overexpressed in tumor tissues and associated with poor survival in the TCGA-BLCA cohort." (PMID 38216619, 2024). "It is assumed that these proteins facilitate the degradation of collagen and elastin fibers and, hence, the tumor growth of bullous pilomatricoma." (PMID 38350760, 2024). "Adhesion to ECM components (such as collagen, elastin, and fibronectin) must be overcome for tumor cell motility and dissemination." (PMID 39338293, 2024). "Gd-ESMA has also been applied to monitor the dynamic changes in elastin deposition in VX2 tumor-bearing rabbits following radiofrequency ablation, offering insight into TME remodeling post-treatment." (PMID 39770505, 2024). "ECM, a non-cellular component, consists of macromolecules including collagen, elastin, fibrin and proteoglycan, which is a significant supporter of the tumor tissues and stromal cells in desmoplastic tumor." (PMID 38644492, 2024). "Compared to a conventional Gd-based MRI contrast agent gadobutrol, elastin-specific ESMA resulted in significantly stronger signal enhancements in the tumor center, tumor margins, and peritumoral regions." (PMID 39770505, 2024).
tumor (continued). "A recent study by our group also explored the effectiveness of the routine elastin staining of all tumor-containing blocks on the detection of venous invasion in CRC specimens." (PMID 37894944, 2023). "LOXL2 is a member of the amine oxidase family, which plays a role in the formation of crosslinks in stromal collagens and elastin, as well as cell motility, tumor development, and progression." (PMID 37886979, 2023). "The main enzymes whose increased activity leads to the degradation of collagen and elastin fibres that accelerates skin aging are collagenase and elastase." (PMID 37373433, 2023). "Lysyl oxidase is a secreted copper-dependent monoamine oxidase that catalyzes the covalent crosslinking of collagen and elastin via oxidation in the tumor microenvironment." (PMID 37891828, 2023). "ECM consists of various molecules, such as laminin, collagen, elastin and fibronectin, and plays a central role in tumour initiation, progression, and metastasis." (PMID 37024866, 2023). "Secretion of LOX by tumor cells leads to cross linking of collagen and elastin and this highly crosslinked collagen matrix contributes to the extensive tumor rigidity and reduced oxygen supply to tumor." (PMID 38022679, 2023). "These proteinases target a wide range of ECM proteins, such as collagen, laminin and elastin, almost all of which were depleted in tumour samples." (PMID 37397358, 2023). "Other molecular probes such as elastin-specific probes and feraheme have shown the feasibility and differentiation between different tumor sizes in terms of elastin content and/or macrophage presence in previous studies." (PMID 36614152, 2022). "Degraded small pieces of ECM (including collagen, elastin, proteoglycans) can be used as tumor biomarkers to measure tumor activity and invasiveness." (PMID 36611857, 2022). "Hematoxylin–eosin staining of the tumor showed a benign papillary lesion comprised of a single layer of endocardial cells, and Elastin staining showed papillary fronds consisting of collagen and elastin fibers." (PMID 35681148, 2022). "The proteases secreted by the MMP family can breakdown proteoglycans, fibronectin, elastin and casein and promote tumor metastasis." (PMID 34974814, 2022). "Except for collagens and elastin, the high molecular weight polymer hyaluronan and its fragments play important roles in cancer development and progression by remodeling the tumor microenvironment and reprogramming cancer metabolism." (PMID 35331296, 2022). "The extracellular matrix is a major structural component of the tumor microenvironment and is comprised of a three-dimensional network consisting of collagens, laminins, elastin and elastic fibers, glycoproteins and proteoglycans." (PMID 35008401, 2022). "First, we used histochemistry and a computerized semi-assisted quantification system to characterize the ECM matrisome (fibrin, hyaluronic acid, elastin, and collagen) in both epithelioid and sarcomatoid tumor cell populations." (PMID 35492318, 2022). "Spatially resolved global approaches, such as spatial transcriptomics, can potentially uncover novel spatial ECM features within TME that can interact with known players such as collagen, elastin, mucin and amyloid to modulate anti-tumor immunity." (PMID 36388913, 2022). "For this, we developed cell-based in vitro functional assays to simulate processes in which cathepsin V is known to play an important role: elastin degradation, tumor cell proliferation, and immune cell cytotoxicity." (PMID 36147668, 2022). "Microscopic examination showed a low-cellular tumor with some thick elastin fibers, which were positive with Verhoeff elastin stain." (PMID 35915504, 2022). "This was possible due to the higher water content and lower collagen and elastin content of the tumor tissues, compared to that of healthy tissues." (PMID 34211794, 2021).
tumor (continued). "As such, investigating the role of elastin fibers as a potential scaffold for neo-angiogenesis or local tumor infiltration in a scenario of incomplete ablation would be of particular value for future research." (PMID 33767303, 2021). "Comparing our two groups, 500 mm3 and 1000 mm3, showed that the group with smaller tumor volumes had a higher SI using the elastin-specific contrast agents." (PMID 34827210, 2021). "Degradation of extracellular matrix proteins such as elastin is considered a prerequisite for the progression of various diseases, including tumor metastases." (PMID 34577799, 2021). "We therefore analyzed the role of elastin in conjunction with molecular MR imaging in a xenograft mouse model, comparing two different tumor sizes." (PMID 34827210, 2021). "Using an elastin-specific molecular probe, we were able to make predictions about the cellular structure in relation to elastin and thus draw conclusions about the size of the tumor, with smaller tumors having a higher elastin content than larger tumors." (PMID 34827210, 2021). "The expressions of HIF‐1α (an indicator of tumor hypoxia), collagen, fibronectin, and elastin (three main components in ECM) were analyzed further to confirm HBO's influence on ECM." (PMID 34085419, 2021). "In conclusion, ECM remodeling following tumor ablation can be readily delineated and quantified at different stages by elastin-specific molecular MR-imaging." (PMID 33767303, 2021). "The LOX family, with five paralogs: LOX and LOX-like 1–4 (LOXL 1–4), play a vital role in catalyzing the cross-linkage of collagen and elastin and thus are involved in the formation of primary tumor and the establishment of metastases." (PMID 34583752, 2021). "LOXL1, like other Lysyl oxidase (LOX) family members, has an established role in modifying the tumor microenvironment by crosslinking collagens and elastin in the extracellular matrix." (PMID 33790946, 2021). "The intravenous administration of the elastin-specific contrast agent resulted in a significant MR signal increase (p ≤ 0.001) in the area of the subcutaneous tumor in all examined mice." (PMID 34827210, 2021). "The crosslinking of collagen and elastin facilitated by LOX enhances the proliferation of tumor cells and promotes metastatic colonization and a fibrotic microenvironment that improves the survival of tumor cells, supporting the development of metastasis." (PMID 34815382, 2021). "In mice with a tumor size of 500 mm3, after application of the elastin-specific contrast agent an SI of 3819 was determined (pre-contrast SI of 907) (p ≤ 0.001)." (PMID 34827210, 2021). "This study shows the feasibility of an elastin-specific MRI molecular probe for the characterization of a PC3 tumor in a SCID mouse model." (PMID 34827210, 2021). "The interaction between the tumor cells and the matrix protein elastin is mediated by elastin-binding proteins (EBPs), S-Gal, and Galectin-3 through the expression and release of elastases." (PMID 34827210, 2021). "Their ratio of elastin to collagen was significantly higher in the tumor fibrous capsule (P < 0.007)." (PMID 33247185, 2020). "The decellularized human tissue employed here provides natural skin stiffness and tissue architecture of collagen and elastin fibres, advancing the study of tumour and immune cell migration and interaction." (PMID 32488012, 2020). "Mass spectroscopic and histopathological quantification of elastin accurately confirmed imaging-derived increases in elastin-specific contrast enhancement on MRI especially in the tumor margins." (PMID 33247185, 2020). "Twelve rabbits with hepatic VX2 tumors were examined using 3 T MRI 14, 21, and 28 days after tumor implantation for two subsequent days (gadobutrol, day 1; elastin-specific probe, day 2)." (PMID 33247185, 2020).
tumor (continued). "ECM, which is mainly comprised of collagens, elastin, fibronectin, laminins, glycoproteins, proteoglycans (PGs) and glycosaminoglycans (GAGs), is an essential and dynamic part of tumor microenvironment." (PMID 33033521, 2020). "The ICP-MS gadolinium concentration (μmol/l) of the whole tumor correlated significantly to histopathological elastin area stains (%) (R = 0.59; P < 0.05) and the elastin-specific MR-based RE (R = 0.73; P < 0.01)." (PMID 33247185, 2020). "Taken together, our data show that ELN plays an important role in regulating tumor cell proliferation and invasion in CRC." (PMID 32171282, 2020). "Molecular MRI using the elastin-specific probe enables the discrimination of the different tumor regions and the peritumoral matrix with a higher accuracy compared to conventional gadolinium-based contrast agents in VX2 hepatic tumors." (PMID 33247185, 2020). "There was also significantly increased ELN mRNA expression in tumors from CRC patients compared to adjacent non-tumor tissues (P = 0.0363)." (PMID 32171282, 2020). "The colocalization of the gadolinium-bound elastin-specific probe with elastic fibers was pronounced in the tumor margin and the peritumoral region and corresponded to increased zinc distribution." (PMID 33247185, 2020). "To access the potential toxicity of elastin to organs, we also performed the same elastin treatment on the non-tumor bearing male BALB/c nude mice." (PMID 33115468, 2020). "Increased ELN mRNA expression is found in tumors from CRC patients compared to non-tumor tissue and healthy controls." (PMID 32171282, 2020). "In comparison to gadobutrol, the elastin probe showed significantly stronger RE, which was pronounced in the tumor margin (day 14–28: P ≤ 0.007)." (PMID 33247185, 2020). "We found ELN gene expression was increased in tumors from CRC patients compared to adjacent non-tumor tissues and healthy controls." (PMID 32171282, 2020). "We found that ELN mRNA expression was significantly increased in tumor tissues from CRC patients compared to those from healthy controls (P = 0.0022)." (PMID 32171282, 2020). "To further understand the role of ELN in regulating tumor development in CRC, we isolated BMDM from mice with over 96% purity." (PMID 32171282, 2020). "This allowed spatial visualisation of collagen and elastin peptides in the tumour microenvironment of FFPE cancer tissues." (PMID 32899238, 2020). "Lysyl oxidases (LOXs) play a central role in extracellular matrix remodeling during development and tumor growth and fibrosis through cross-linking of collagens and elastin." (PMID 30676771, 2019). "After being released by tumor cells, these proteolytic enzymes break down components of the ECM such as collagen, laminin and elastin, thereby allowing for the dissemination of primary tumor cells." (PMID 31824841, 2019). "This leads to an increased cross-linking of collagens and elastin, rendering the tumor more rigid and contributing—in combination with the already increased ECM deposition—to its palpability." (PMID 32118030, 2019). "This contributes to bioactive matrix fragment (Matrikine) accumulation like elastin degradation products (EDP) stimulating tumour cell invasive and metastatic properties." (PMID 30739912, 2019). "In this study, we identified and characterized collagen and elastin fibers in the normal prostate and canine PC (inside the tumor) using PSR and IHC tests." (PMID 30832371, 2019). "During tumour progression, elastin is cleaved by many proteinases secreted locally or circulating in serum." (PMID 30739912, 2019). "The tumor stroma is composed of elastin, collagens, fibronectin, laminins, and cellular proteases, such as cathepsins and matrix metalloproteinases." (PMID 31661894, 2019). "This feature correlates well with histopathological examination, findings, and SHG in particular shows collagen and elastin bundles around the tumor." (PMID 31824956, 2019).